ENSG00000268133 (novel protein)
Gene: Protein-coding gene on chromosome 19 (57,363,566 to 57,398,584, forward strand). Ensembl gene ENSG00000268133.
Genetic constraint (gnomAD): Loss-of-function variants: 5 observed, 7.89 expected, observed/expected ratio (o/e) 0.63, 90% interval 0.33 to 1.33. That is too few expected variants to judge how well the gene tolerates losing a copy. Missense variants: 117 observed, 125.99 expected, observed/expected ratio (o/e) 0.93, 90% interval 0.8 to 1.08. Synonymous variants: 35 observed, 47.7 expected, observed/expected ratio (o/e) 0.73, 90% interval 0.56 to 0.97.